MT1JP (metallothionein 1J, pseudogene )
Diseases named in the same sentence as MT1JP in open-access papers (continued):
Sharing a sentence is not in itself a finding about the gene and the disease.
tumor (26 papers, 2016 to 2025). "This indicates that MT1JP exerts its tumor-suppressing effects in ICC by regulating the miR-18a-5p/FBP1 axis." (PMID 39458127, 2024). "Functionally, overexpression of MT1JP was found to inhibit cell proliferation, migration and invasion, promote cell apoptosis in vitro and slow down tumor growth and metastasis in vivo." (PMID 35270630, 2022). "In retinoblastoma, MT1JP plays a tumor suppressive role via targeting Wnt/β-catenin signaling pathway." (PMID 35928868, 2022). "LncRNA metallothionein 1 J, pseudogene (MT1JP) has been reported to play tumor-suppressing roles in multiple cancers." (PMID 33557774, 2021). "For example, LncRNA MT1JP can suppress cell growth, migration, and invasion, promote cell apoptosis in vitro, and inhibit tumor growth and metastasis in vivo." (PMID 34307360, 2021). "Further, hsa-miR-532-3p along with hsa-miR-139 are associated with CHRD, FLAD1, MT1JP, and EBF2 in our analysis and have been identified as tumor suppressors in HCC that inhibit cell proliferation, migration, and invasion." (PMID 32228601, 2020). "Functionally, overexpression of lncRNA MT1JP inhibited cell proliferation, migration, invasion and promoted cell apoptosis in vitro, and inhibited tumor growth and metastasis in vivo." (PMID 29720189, 2018). "One recent study implied that the lncRNA MT1JP played a potential role in promoting apoptosis to restrain the growth of tumour cells." (PMID 27966580, 2016). "In the present study, we report a lncRNA named MT1JP which acts as a tumor suppressor through a posttranscriptional mechanism." (PMID 26909858, 2016). "We found that MT1JP is differentially expressed in tumor tissues by analyzing data from a customized microarray applied to 76 pairs of matched normal and cancer tissue samples." (PMID 26909858, 2016). "To further investigate the effects of MT1JP on tumor inhibition, we constructed a plasmid for overexpression of MT1JP in HepG2 and SMMC-7721 cells, which normally express MT1JP at lower levels than L02 cells." (PMID 26909858, 2016). "Together, our results suggest that MT1JP is a novel tumor suppressor, and broaden our knowledge of the development of human tumors." (PMID 26909858, 2016). "In line with the microarray analysis, we found that MT1JP had considerably lower expression in almost all tumor samples." (PMID 26909858, 2016). "Our data show that MT1JP has considerably lower expression in tumor tissue samples than in matched normal tissue ones, which was observed among samples from gaster, colon, liver and lung." (PMID 26909858, 2016). "In vivo data revealed that lncRNA MT1JP reduced tumor sizes and tumor metastasis." (PMID 35928868, 2022).
tumor (continued). "Bi et al28 showed the putative tumor‐suppressor role of MT1JP by negatively modulating the action of the Wnt/β‐catenin signaling pathway in the development of RB and that it may also be used as a prognostic biomarker and therapeutic target." (PMID 31038819, 2019). "Since MT1JP may have a role as a tumor suppressor in several kinds of cancers, it is likely that the translational regulation by the MT1JP protein complex demonstrated in this study is a widely occurring tumor suppression phenomenon." (PMID 26909858, 2016). "To address whether MT1JP exert its effects as a tumor suppressor, we first investigated in more detail the role of MT1JP in tumor suppression." (PMID 26909858, 2016). "More generally, its consistent expression pattern in numerous tumor specimens indicates that MT1JP may be a significant biomarker of diagnosis with a potential in cancer therapy." (PMID 26909858, 2016). "Similarly, the LncRNA MT1JP inhibits tumor growth by negatively regulating the Wnt/β‐catenin signaling pathway, suggesting that MT1JP may serve as a prognostic biomarker and therapeutic target." (PMID 35592755, 2022). "MT1JP adsorbs miR-92a-3p to target and regulate the expression of FBXW7, which is a tumor suppressor molecule that plays an important role in tumor apoptosis, epithelial cell differentiation, and drug resistance in GC." (PMID 39210921, 2024). "In summary, our study confirmed the anti-tumor effect of MT1JP on TNBC, and MT1JP inhibited the progression of TNBC possibly by upregulating miR-138 and inhibiting HIF-1α." (PMID 35703312, 2022). "Except for MT1JP and BDNF-AS, which are down-regulated and act as a tumor suppressor gene in RB, other lncRNAs are all up-regulated in RB and promote RB progression." (PMID 30905893, 2019). "We analyzed the expression and function of MT1JP in TNBC and found that MT1JP was downregulated in TNBC and may play a tumor suppressive role by upregulating miR-138, which can direct target HIF-1α." (PMID 35703312, 2022). "In ICC, several lncRNAs such as lncRNA MT1JP and lncRNA AGAP2-AS1 have been shown to exhibit their tumor-related effects via sponging miRNAs to modulate the expression of various genes involved in tumor progression." (PMID 34239888, 2021). "In line with in vitro analysis, the results indicated that the volume and weight of xenograft tumor were significantly lower in MT1JP overexpression group as compared with negative control group." (PMID 29720189, 2018). "We further identified a significant positive correlation between MT1JP and the expression of miR-138, and a significant negative correlation between MT1JP and the expression of HIF-1α in tumor tissues." (PMID 35703312, 2022). "Furthermore, knockdown of MT1JP resulted in a range of changes which usually arise during tumor formation, including cell cycle arrest, apoptosis inhibition, proliferation acceleration, and increased invasion and migration, as opposed to the effects of MT1JP overexpression." (PMID 26909858, 2016).
cancer (8 papers, 2016 to 2022). A tumor composed of atypical neoplastic, often pleomorphic cells that invade other tissues. "MT1JP, a down-regulated lncRNA in GC, was associated with malignant tumor phenotypes and survival of GC." (PMID 29720189, 2018). "Even more importantly, the association between MT1JP and RNA-binding protein provides a novel node in the complicated cancer regulatory network." (PMID 26909858, 2016). "Down- or up-regulation of MT1JP led to variation in the expression of numerous cancer-associated mRNA molecules." (PMID 26909858, 2016). "The survival time was significantly lengthened in cancer patients with a higher expression level of MT1JP." (PMID 35270630, 2022). "A previous study has extensively investigated the expression of MT1JP in cancers developed from four types of organ." (PMID 35703312, 2022). "The MT1JP was decreased and miR-18a-5p was increased in intrahepatic cholangiocarnoma tissues, compared with para-carcinoma tissues, which was consistence with data from TCGA database." (PMID 33557774, 2021). "We validate our analysis via the public dataset and also sum up the studies of lncRNA BDNF-AS and MT1JP in other cancers." (PMID 32514246, 2020). "In order to select one or more cell lines for functional studies of this lncRNA, we examined the MT1JP expression in several cell lines derived from normal or cancer cells of three kinds of tissues." (PMID 26909858, 2016). "To investigate which pathway MT1JP might be involved in, we conducted a Gene Ontology (GO) analysis of genes whose expression was strongly correlated (r2 > 0.25) to that of MT1JP in the normal and matched cancer tissues." (PMID 26909858, 2016).
infection (1 paper, 2016). The state of being infected such as from the introduction of a foreign agent such as serum, vaccine, antigenic substance or organism. "In our microarray data, the expression of MT1JP in macrophages with H37Ra infection was significantly higher than that with H37Rv infection." (PMID 27966580, 2016).
MT1JP also shares sentences with these, for which no sentence is quoted: hepatocellular carcinoma (3 papers); acromegaly (1); glioblastoma (1); triple-negative breast carcinoma (1).